IL6 (interleukin 6)
Diseases named in the same sentence as IL6 in open-access papers (continued):
Sharing a sentence is not in itself a finding about the gene and the disease.
cerebral aneurysm (14 papers, 2012 to 2025). "Studies have shown that IL-6 can enhance macrophage infiltration in the cerebral arterial circle, promoting the rupture of estrogen-deficient-related cerebral aneurysms in mice." (PMID 39253091, 2024). "IL-6 is increased in the serum of estrogen-deficient mice and appears to contribute to the rupture of estrogen-deficient cerebral aneurysm in mice by enhancing macrophage infiltration at the circle of Willis." (PMID 37041519, 2023). "Much like TBI, ruptured brain aneurysms also induce an influx of peripheral immune cell infiltration into the brain, and increases in IL1β, IL-6, MCP1, and TNF have been associated with poor outcomes for both." (PMID 31711546, 2019). "A recent meta-analysis of 8 genes and 13 polymorphisms in approximately 20,000 individuals found a strong association between IL-6 gene polymorphism and cerebral aneurysm." (PMID 23316103, 2012). "Formation of a cerebral aneurysm is also associated with overproduction of Il-6 by an emboli tumor, that induces degradation of the extracellular matrix in the intracranial vessels and is connected with an increased level of IL-6 in cerebrospinal fluid." (PMID 36675669, 2022). "Recent studies have shown that there is a connection between overproduction of Il-6 and cerebral aneurysm development." (PMID 36675669, 2022). "A recent study found differential (lower) expression of IL-6 and upregulation of other inflammatory mediators in cerebral aneurysm as compared to middle temporal artery tissues." (PMID 33923626, 2021). "Together, these and other published data support the concept of IL-6 as a prominent player in the pathophysiology of cerebral aneurysms." (PMID 33923626, 2021). "The results of this study show that elective cerebral aneurysm surgery is followed by increased IL-6 concentrations in plasma and increased IL-6 and IL-1β concentrations in CSF." (PMID 34472736, 2021). "Primary aim of this trial is to determine the influence of local anesthesia with lidocaine on the perioperative levels of pro-inflammatory cytokines interleukin-1β, interleukin-6, and tumor necrosis factor-α in plasma and CSF in cerebral aneurysm patients." (PMID 31626100, 2019). "Specifically, smokers have higher levels of IL-1β, TNFα, and IL-6, all of which significantly contribute to the pathobiology of cerebral aneurysm." (PMID 23316103, 2012). "Based on recent data, any relationship between SARS-CoV-2 infection and cerebral aneurysm rupture could possibly involve macrophage-mediated production of interleukin-1β, interleukin-6, and tumor necrosis factor-α." (PMID 35386414, 2022). "Adjunctive lidocaine-based scalp block and laryngotracheal local anesthesia might attenuate CSF IL-6 concentration increase in patients with brain aneurysm." (PMID 34472736, 2021). "Moreover, regular cardiac myxomas are prone todevelop cerebral aneurysms and highly elevated serum IL-6." (PMID 30810670, 2019). "IL-6 may also have an important role in cerebral aneurysm pathogenesis according to several genetic case-control studies." (PMID 23316103, 2012). "Sitosterol can treat cerebral aneurysms by reducing the expression of chemokines and inflammatory cytokines TNF-α, IL-8, IL-1β, IL-17, IL-6, and MMP-2/9." (PMID 33149752, 2020). "The primary aim was to determine the effect of adjunctive regional/topical lidocaine anesthesia on perioperative temporal profile of pro-inflammatory cytokines concentrations (IL-1β, IL-6, and TNF-α) in plasma and CSF of cerebral aneurysm patients undergoing elective open surgery." (PMID 34472736, 2021). "Trial will test the hypothesis that lidocaine administration decreases concentrations of IL-1β, IL-6, and TNF-α in plasma and CSF in patients undergoing cerebral aneurysm surgery." (PMID 31626100, 2019).
chronic myeloid leukemia (14 papers, 2013 to 2025). "Inflammatory signals may provide these hits, as suggested in a mouse model of human chronic myelogenous leukemia in which IL-6 secreted by mature myeloid cells contributes to leukemic progenitor cell development." (PMID 35115654, 2022). "CT inhibited p-STAT5 and p-STAT3, effectively blocked IL-6–mediated STAT3 activation, and reversed chronic myeloid leukemia (CML) fusion gene (BCR-ABL) kinase-independent drug resistance and inhibited key cell coproliferation and drug resistance pathway of K562/ADR in CML." (PMID 32265690, 2020).
colon adenocarcinoma (14 papers, 2003 to 2025). "The MC-38 cell line derived from C57BL/6 murine colon adenocarcinoma cells can be employed as it has expressed PD-L1 and secretory IL-6." (PMID 37924094, 2023). "To assess the removal of IL-8 and IL-6 by the engineered bacteria, we established inflammatory cell models by stimulating cytokine secretion in human colon adenocarcinoma cells (Caco-2; HT-29) and monocyte-like cells (THP-1; U-937)." (PMID 35155394, 2022). "Moreover, the engineered bacteria removed a high proportion of the IL-8 from the supernatants of immunostimulated Caco-2 and HT-29 colon adenocarcinoma cell lines, and depleted IL-6 from the supernatants of immunostimulated THP-1 and U-937 monocyte-like cells." (PMID 35155394, 2022). "LRG1 expression can be induced by TNF-α, IL-6, and IL-22 in human colon adenocarcinoma cell line." (PMID 32249825, 2020). "Notably, the immediate short-term growth inhibitory effect of IL6 supplementation may inspire a novel case-dependent preoperative drug regimen candidate that is likely to reduce the aggressiveness of colon adenocarcinoma." (PMID 32341349, 2020). "In the current work, we studied the effect of human colon adenocarcinoma-derived TAFs and their normal tissue counterparts, naive fibroblasts, on colon cancer growth oscillation and clock protein expression and analysed the effect of naive fibroblast-secreted IL6 on HCT116 cells." (PMID 32341349, 2020). "In agreement with our results, Takenaga (1999) showed that the expression of S100A4 in human colon adenocarcinoma cell lines was regulated by IFN-γ, but not influenced by IL-1, IL-6, various growth factors or IFN-α and -β." (PMID 12799648, 2003).
cryptococcosis (14 papers, 2013 to 2025). An acute or chronic, localized or disseminated infection by Cryptococcus neoformans. "Therefore, we evaluated how IL-6 deficiency impacted GXM accumulation in tissue during cerebral cryptococcosis." (PMID 39334365, 2024). "Hence, we examined how IL-6 deficiency alters the morphology of microglia during cryptococcal infection at 3- and 7-dpi." (PMID 39334365, 2024). "We searched for the presence of auto-Abs against nine cytokines (IFN-α, IFN-β, IFN-ω, IFN-γ, IL-12p40, IL-17 A, IL-23, IL-6 and GM-CSF) in the serum samples of the 30 patients with cryptococcosis." (PMID 39008214, 2024). "We also provided significant evidence demonstrating that IL-6 is an important immunomodulator and influences glial responses and effector functions against cryptococcal infection." (PMID 39334365, 2024). "We compared the survivability and pathophysiology of disseminated cryptococcosis in Wild-type, IL-6−/−, and IL-6−/− mice supplemented with exogenous IL-6." (PMID 39334365, 2024). "Intracerebral challenge of mice with exogenous IL-6 enhances survival during cryptococcal infection by reducing fungal load in blood and brain." (PMID 39334365, 2024). "Blasi also showed that exogenous and local (intracerebrally; i.c.)IL-6 supplementation of Wild-type mice prior to i.c. cryptococcal infection significantly reduced blood and brain fungal load, resulting in prolonged survival." (PMID 39334365, 2024). "Using an IL-6 knock-out (KO) mouse model of systemic Cn infection, we demonstrated and validated the importance of this multifunctional cytokine on disseminated cryptococcosis, particularly focusing on fungal brain invasion and colonization." (PMID 39334365, 2024). "Since Wild-type mice actively produce IL-6 early during cryptococcal infection, these animals were able to limit the inflammatory response to localized regions of the lungs while keeping the fungal burden lower than IL-6−/− and IL-6−/− + rIL-6 groups." (PMID 39334365, 2024). "Our results suggest IL-6 is an essential cytokine for the protective immune response against murine cryptococcosis." (PMID 30401972, 2018). "Further studies investigating the impact of immunomodulator molecules such as IL-6 on cerebral cryptococcosis are warranted for the development of antifungal therapy or treatments aimed to prevent, reduce, or manage Cn infections especially in at-risk immunosuppressed populations." (PMID 39334365, 2024). "Therefore, we assessed the astrocytic responses and morphological changes in brain tissue of Wild-type, -IL-6−/−, and -IL-6−/− + rIL-6 following systemic cryptococcal infection at 3- and 7-dpi." (PMID 39334365, 2024). "Thus, survival in HIV and cryptococcosis co‐infection is associated with higher expression of pro‐inflammatory cytokine responses (IFN‐γ, TNF‐α and IL‐6) and corresponding higher influx of white blood cells that infiltrate the cerebrospinal fluid." (PMID 32472727, 2020). "Together, the influence of IL-6 and cryptococcal infection could promote poor antigen clearance, persistence of residual antigen, and subsequent risk of CM-IRIS, consistent with the elevated serum CrAg titer among those pre-disposed to CM-IRIS." (PMID 29371546, 2017). "Lastly, astrogliosis was high and moderate in infected brains removed from Wild-type and IL-6−/− supplemented with rIL-6 animals, respectively, while minimal astrogliosis was observed in IL-6−/− tissue, highlighting the potential of astrocytes in containing and combating cryptococcal infection." (PMID 39334365, 2024). "When comparing the cytokines that these cells are capable of producing with the cytokines known to be induced by cryptococcal infections in the brain, a small list is generated: CXCL10, IL6, CCL5, and IFN-γ." (PMID 40985448, 2025). "To evaluate the importance of IL-6 in controlling cryptococcosis, we infected Wild-type C57BL/6, IL-6−/−, and IL-6−/− supplemented with recombinant (r) IL-6 (40 pg/g/day) mice with Cn strain H99 cells." (PMID 39334365, 2024).
cryptococcosis (continued). "To test this, we quantified levels of seven cytokines and chemokines (interferon-γ (IFN-γ), TNF-α, interleukin-1b (IL-1b), interleukin-6 (IL-6), MCP-1, G-CSF and GM-CSF) in the media immediately following cryptococcal infection and again 18 hours later." (PMID 29596441, 2018). "During cryptococcal infection, the lack of host 5-LO had the opposite effect on the production of proinflammatory cytokines like IL-6, G-CSF, and CCL2, suggesting that Cryptococcus can stimulate the production of these cytokines independently of the host LTB4." (PMID 39082787, 2024). "Their roles include production of pro‐inflammatory cytokines, including IL‐6, TNF‐α and IFN‐γ,114 that may influence the extent of cryptococcosis‐induced inflammation, immune activation and host damage responses." (PMID 32472727, 2020). "It was associated with a low peripheral CD4 count, reflecting the importance of cell-mediated immunity in controlling cryptococcal infection, and with a poor inflammatory response at the site of infection, as evidenced by low CSF white cell counts and low levels of IFN-γ, TNF-α, and IL-6." (PMID 24319084, 2014). "Indeed, in murine cryptococcosis MCP-1 was shown to control the early production of pro-inflammatory cytokines such as TNF-α and IL-6, the recruitment of mononuclear cells to infected lungs and the immunoprotection mediated by Th1 immunity." (PMID 24205424, 2013). "Severe cryptococcosis in the FcγRIIb−/− mice was demonstrated by high fungal burdens in the internal organs with histological cryptococcoma-like lesions and high levels of TNF-α and IL-6, but not IL-10." (PMID 28074867, 2017).
ductal carcinoma (14 papers, 2010 to 2025). "When compared to healthy people, serum IL-6 levels were much higher in ductal carcinomas, indicating that a high level of IL-6 was associated with poor survival." (PMID 37520246, 2023). "This was evidenced by the fact that IL-6 serum levels in patients with ductal carcinoma were significantly higher than in healthy women." (PMID 38793599, 2024). "Extracellular IL-6 induces malignant features in stem/progenitor cells from ductal breast carcinoma." (PMID 32033472, 2020). "IL-6 triggers malignant features in human ductal breast carcinoma and IL-6-STAT3 signaling cascade is important for epithelial tumorigenesis and dissemination." (PMID 20520770, 2010). "In this study, we try to evidence that IL-6 gene expression is upregulated in MS obtained from aggressive ductal breast carcinomas and that IL-6 regulates a Notch-3-dependent signaling pathway that promotes self-renewal and the invasive potentials of normal and tumor MS." (PMID 25881039, 2015). "In conclusion, our data support the hypothesis that IL-6 induces malignant features in Notch-3-expressing, stem/progenitor cells from human ductal breast carcinoma and normal mammary gland." (PMID 25881039, 2015).
gallbladder cancer (14 papers, 2016 to 2025). "Sesamin directed the epithelial differentiation of cancer stem-like side population cells from gallbladder cancer, which is negatively associated with the NF-κB/IL-6/STAT3/Twist signaling pathway." (PMID 40303286, 2025). "Cancer-associated fibroblasts promote gallbladder cancer growth via activation of the IL6-JAK/STAT3 signal pathway." (PMID 33768003, 2021). "After cultured with aprepitant for different time, gallbladder cancer cells generated more inflammatory cytokines including IL‐6, IL‐1β and TNF‐α." (PMID 37221457, 2023). "MOB1A furthered the survival of gallbladder cancer by inducing autophagy to reduce cellular apoptosis and activate the IL6/STAT3 signaling pathway." (PMID 37314589, 2023). "Previous study has reported that IL6 was up-regulated in gallbladder cancer tissues and promoted cell proliferation, and invasion." (PMID 34165442, 2021). "For example, the overexpression of IL-6 enhances the invasion and migration of gallbladder cancer cells, by stimulating EMT." (PMID 28208810, 2017). "In gallbladder cancer, CAFs can promote VM formation and tumour growth by upregulating NOX4 expression through activation of the IL-6-JAK-STAT3 signalling pathway." (PMID 38459564, 2024). "Corroborating these findings, a study of cholangiocarcinoma and gallbladder cancer found upregulation of both APOEBC3A and APOBEC3B with IL-6 and TNF-α exposure." (PMID 36978147, 2023).
generalized anxiety disorder (14 papers, 2020 to 2025). An anxiety disorder characterized by excessive and difficult-to-control worry about a number of life situations. "The inflammatory markers TNF-α and IL-6 are also higher in the blood of individuals with major depression, and generalized anxiety disorder (GAD)." (PMID 37706039, 2023). "One study showed that while patients with both PD and generalized anxiety disorder (GAD) showed higher IL-6 compared to healthy individuals, PD subjects had even greater IL-6 than individuals with GAD." (PMID 36523875, 2022). "Additionally, a large cohort study demonstrated significantly higher levels of IL-6 in individuals with generalized anxiety disorder (GAD)." (PMID 39757257, 2025).
Heat Stroke (14 papers, 2014 to 2026). A condition caused by the failure of body to dissipate heat in an excessively hot environment or during PHYSICAL EXERTION in a hot environment. "Blood malondialdehyde, advanced protein oxidation product, protein carbonyl, 8-hydroxydeoxyguanosine, and interleukin-6 levels in patients with severe heat stroke were significantly elevated." (PMID 42079625, 2026). "Our research findings also indicate significantly increased NF-κB expression in the liver of the DHC group compared with that in the NC group, indicating that heat stroke caused inflammatory responses in the body in a process involving TNF-α and IL-6." (PMID 38553498, 2024). "In our results, TNF-α and IL-6 were rapidly increased upon infection and heat stroke which was also previously reported." (PMID 34092247, 2021). "This study also lacked additional biomarkers associated with heat stroke, such as IL-6, LPS, BNP, FDP, μMb, and BE." (PMID 39802884, 2024). "Previous studies have demonstrated that SMS treatment could ameliorate cerebral iNOS reactivity and NO production, and reduce serum levels of TNFα, IL-1β, and IL-6 in heat stroke rats." (PMID 39156108, 2024). "Moreover, IL‐6 played a strong roles in promoting inflammation in the pathogenesis of MODS secondary to heat stroke." (PMID 37904703, 2023). "Therefore, in the present study, we investigated changes in serum concentrations and clearance of the pro-inflammatory factors TNF-α and IL-6 and the anti-inflammatory factor, IL-10, in dogs following the induction of heat stroke and HF." (PMID 25145441, 2014). "The research reveals that heat stroke triggers an early and complex systemic inflammatory response, marked by the simultaneous release (rather than a sequential release) of pro‐inflammatory cytokines such as IL‐6 and IL‐8, and anti‐inflammatory cytokines like IL‐10." (PMID 38124439, 2024). "In addition to AP‐1 and NF‐κB signaling, changes in IL‐6 transcript and protein abundance may represent a key difference between acute (heat stroke) and prolonged exposure to environmental hyperthermia." (PMID 28830980, 2017). "Serum concentrations of all solutes tended to increase with time after heat stroke in the control group, but decreased (BUN, creatinine) or remained relatively unchanged (TNF-α, IL-6, IL-10) with time in the HF group." (PMID 25145441, 2014). "Serum concentrations of interleukin (IL)-10, tumor necrosis factor (TNF)-α, IL-6, blood urea nitrogen (BUN) and creatinine were measured at baseline and 1, 2, and 3 h after heat stroke." (PMID 25145441, 2014). "We found that in the 3 hours after the induction of heat stroke, serum concentrations of TNF-α, IL-6, IL-10, BUN, and creatinine continued to increase in the control group of dogs, but not in the group of dogs that subsequently received HF." (PMID 25145441, 2014). "Of note, during the 1 to 3 hour post-heat stroke induction period, serum concentrations of TNF-α, IL-6, IL-10, BUN, and creatinine were significantly lower in dogs that received HF than in dogs that did not receive HF." (PMID 25145441, 2014). "This reveals that an exaggerated anti-inflammatory cytokine response may worsen heatstroke outcomes, which is further demonstrated by IL-6 and TNF-α knockout mice showing higher classic heat stroke-related mortality." (PMID 39619011, 2024). "Pro-inflammatory cytokines including IL-1β, IL-6, and TNF-α are elevated in both infection and heat stroke, suggesting infection might prime a latent immune response that is synergistically driven by heat challenge and promoted severe pathology." (PMID 34092247, 2021). "HF prevents heat stroke-induced increases in serum cytokine concentrations and is effective for clearing small molecular weight solutes from serum, but less effective for clearing larger molecular weight solutes, including TNF-α, IL-6, and IL-10." (PMID 25145441, 2014).